KRAS (KRas proto-oncogene, GTPase)
Diseases named in the same sentence as KRAS in open-access papers (continued):
Sharing a sentence is not in itself a finding about the gene and the disease.
colorectal cancer (continued). "Evidence has been provided that IDH1/2 mutants are more frequent in colorectal cancers showing CpG island methylator phenotype, often concurrent with KRAS/BRAF mutations, although with a lower allelic frequency." (PMID 37064137, 2023). "In recent years, we have witnessed a growing interest in the predictive and prognostic significance of the KRAS mutation in colorectal cancer patients." (PMID 36836752, 2023). "Considering what has been said until now, KRAS-mutated colorectal cancers, given the complexity of the pathology, deserve a personalized approach." (PMID 36836752, 2023). "One patient with pancreatic cancer and four patients with colorectal cancer showed mutations in the KRAS gene." (PMID 36991390, 2023). "The present study aims to provide a synthetic and comprehensive review of deep neural networksmodels for predicting the d-MMR/MSI status and BRAF/KRAS mutational status in colorectal cancer." (PMID 38201408, 2023). "Here we show that MSI-H, MLH1 hypermethylation, BRAF mutation or KRAS mutations were independently associated with Fn infection in colorectal cancer." (PMID 37772997, 2023). "The utilization of these other therapies in conjunction with the direct inhibitors provides a significant step forward in the treatment of KRAS mutated colorectal cancers." (PMID 37190303, 2023). "More than 30% of all human cancers are driven by RAS mutations and activating KRAS mutations are present in 40% of colorectal cancer (CRC) in the two main CRC subgroups, MSS (Microsatellite Stable) and MSI (Microsatellite Instable)." (PMID 37020037, 2023). "This study focused on an analysis of the ncRNA, sRNA, and miRNA that were consistently up or downregulated after administration of the reovirus treatment for KRAS-mutated colorectal cancer." (PMID 37873786, 2023). "On the other hand, the frequency of KRAS mutations in appendiceal cancers (51%; with a maximum of 56% in adenocarcinomas) is close to that in colorectal cancers (51.8%) and small bowel cancers (53.6%), but much higher compared to gastric cancers (14.2%)." (PMID 37509254, 2023). "Changes in the KRAS gene and Akt proteins, expression levels of miR-99b and miR-135b, and factors affecting survival were compared between colorectal cancer-associated peritoneal carcinomatosis and liver metastasis." (PMID 37639911, 2023). "KRAS mutations are known to be associated with poor prognosis in colorectal cancer patients, due to their role in determining drug resistance and their prevalence in right-sided colon tumors." (PMID 37628934, 2023). "Another study confirmed that VDR expression is associated with the PI3K-AKT pathway and KRAS mutation in colorectal cancer." (PMID 37561808, 2023). "Studies have shown that the tumor microbiome in colorectal cancer can be distinguished from non-KRAS mutated samples by ML, suggesting a possible association between tumor microbiome and tumor mutations." (PMID 37573394, 2023). "These variants have been studied and associated with different types of cancer in diverse populations but not in the Mexican population, where studies on the association between KRAS gene variants and colorectal cancer are limited." (PMID 37566020, 2023). "We conducted these experiments using HCT116 cells, a well-established model of colorectal cancer encoding the oncogenic KRAS G13D and PIK3CA H1047R proteins." (PMID 37811895, 2023). "Research into the best combinations of KRAS inhibitors with other drugs is thriving, including studies targeting more common KRAS mutations in colorectal cancers, such as KRAS G12D." (PMID 37909027, 2023). "Considerable effort has been made in recent years to give access to precision medicine to patients with KRAS-mutated colorectal cancer." (PMID 36836752, 2023). "A change in KRAS/MAPK signaling or a BRAF or KRAS gene mutation causes drug resistance in MEK1/2 inhibitors in cancer cells like colorectal cancer, ovarian cancer, and others." (PMID 37418080, 2023).
colorectal cancer (continued). "Regarding KRAS G12/G13 mutations, 44.6% (45/101) of colorectal cancer with KRAS mutations (KRAS mutated-CRC) were infected with Fn." (PMID 37772997, 2023). "Colorectal cancer (CRC) cells harboring KRAS or BRAF mutations show a more-malignant phenotype than cells with wild-type KRAS and BRAF." (PMID 37972012, 2023). "This cross-sectional study investigates the association of KRAS sequence variation with survival among patients with young- vs late-onset colorectal cancer." (PMID 38032636, 2023). "This is consistent with the poor prognosis of G12V and G12C mutation colorectal cancers we reported compared to wild-type KRAS colorectal cancers." (PMID 37758931, 2023). "This was discovered in colorectal cancer cells having KRAS G13D mutations that became resistant to MEKi." (PMID 38201521, 2023). "Two prior studies have found that a combination of navitoclax and AZD8055 synergistically kills different tumor cells from SCLC and BRAF/KRAS-mutated colorectal cancer." (PMID 36588105, 2023). "Since colorectal cancers with KRAS mutations are a heterogeneous group, the frequency of these mutations can also vary among different populations." (PMID 37628934, 2023). "Despite this, there are still limited data on the mutational status of KRAS amongst colorectal cancer (CRC) patients in Malaysia." (PMID 36899966, 2023). "Examination of KRAS mutations showed 28/58 (43.8%) patients with colorectal cancer, while HER2 overexpression was found in 6/58 (10.3%) patients with colorectal cancer." (PMID 37228916, 2023). "The low prevalence of KRAS mutations in colorectal cancer limits KRAS in combination with other biomarkers." (PMID 38018033, 2023). "Our results show that Fn infection is enriched in clinically distinctive subgroups of colorectal cancers, MSI-H, and KRAS-mutated colorectal cancers." (PMID 37772997, 2023). "In this cross-sectional study of 21 661 patients with colorectal cancer, KRAS sequence variation was associated with worse survival compared with KRAS wild type in patients with young- and late-onset cancer." (PMID 38032636, 2023). "Mutations of the APC, TTN, MUC16, and KRAS genes were high in frequency in both colorectal adenoma and colorectal cancer samples." (PMID 37546388, 2023). "The understanding of the association between KRAS sequence variation status and clinical outcomes in colorectal cancer (CRC) has evolved over time." (PMID 38032636, 2023). "The KRAS mutation is present in 30–50% of colorectal cancers, and this mutation is associated with worse survival, so it is considered a negative prognostic factor." (PMID 37626641, 2023). "Together with the location of colorectal cancer, professional guidelines have focused on tumor KRAS mutation as a main factor to be considered in treatment choices." (PMID 37511664, 2023). "According to statistics, KRAS mutations exist in more than 90% of pancreatic ductal adenocarcinomas (PDACs), 40% of colorectal cancers, and 35% of non-small cell lung cancers (NSCLCs)." (PMID 38111008, 2023). "In KRAS-mutated colorectal cancers, trametinib leads to the attenuation of MEK/ERK pathways, similar to the effect of ARID1A loss in these cells." (PMID 36658200, 2023).
colorectal cancer (continued). "In colorectal cancer, the prevalence of KRAS mutations in MSI cases is lower than in MSS, where it reaches 46%." (PMID 37190216, 2023). "We previously reported that KR12, a DNA‐alkylating pyrrole‐imidazole polyamide designed to recognize the KRAS G12D/V mutation, showed an anti‐tumor effect in colorectal cancer." (PMID 36262061, 2023). "Vitamin C was found to act in a novel, multi-faceted mechanism to inhibit KRAS-mutated colorectal cancer cells." (PMID 37190303, 2023). "Taken together, these results showed that MSI-H, BRAF mutations, MLH1 hypermethylation, and KRAS mutations are independently associated with Fn infection in colorectal cancer." (PMID 37772997, 2023). "KRAS G12V/G12D/G12S/G13D mutations were suggested to confer resistance to anti-EGFR antibody therapies in colorectal cancer patients." (PMID 37511664, 2023). "In KRAS-mutated colorectal cancer, CHD1 protein is hyper-SUMOylated by the SUMO E2 ligase UBC9, and depletion of CHD1 impairs the KRAS-driven transformation." (PMID 36776288, 2023). "Colorectal cancer (CRC) is often caused by mutations in the KRAS oncogene, making KRAS neoantigens a promising vaccine candidate for immunotherapy." (PMID 37240273, 2023). "On the contrary, our group found that nuclear HES1 expression is lost in 91% of sessile serrated adenomas/polyps (SSA/p) and most of the right-sided colorectal cancer which commonly harbors BRAF or KRAS mutation." (PMID 37749297, 2023). "Currently, the detection of KRAS mutation is routinely carried out in colorectal cancer patients on FFPE tumor tissue." (PMID 37511664, 2023). "The JAK1/2-STAT pathway was found to be upregulated after MEK inhibition in KRAS-mutated colorectal cancers." (PMID 37190303, 2023). "The use of Vitamin C has had varied responses in clinical trials; there are currently two trials looking at Vitamin C in colorectal cancer patients with KRAS mutations." (PMID 37190303, 2023). "Nearly 70 % of the mutations occur in KRAS, mainly in pancreatic cancers (86 %), colorectal cancers (CRC; 41 %) and lung cancer (32 %)." (PMID 36313934, 2023). "The mutant KRAS peptide vaccine comprises a mixture of six 21-amino-acid-long synthetic peptides encompassing common KRAS hotspot mutations in pancreatic and colorectal cancer—five alterations at the G12 position and one alteration at the G13 position." (PMID 37776855, 2023). "KRAS mutations are fraught with the progression of colorectal cancer and resistance to chemotherapy." (PMID 37069612, 2023). "The potential clinical utility of trtDNA analysis is emerged also in colorectal cancer (CRC) where KRAS and BRAF mutation profile detected in urine overlapped with matched tumor tissue and plasma." (PMID 37542343, 2023). "The frequency of RAS mutations in colorectal cancer has been reported to be 50%–60% for KRAS, NRAS, and HRAS." (PMID 37760533, 2023). "Alternatively, Fn preferentially colonizes colorectal cancers with SSP and KRAS mutations but can expand more in colorectal cancers with SSP." (PMID 37772997, 2023). "Colorectal cancers (CRC) with KRAS mutations (KRASmut) are frequently included in consensus molecular subtype 3 (CMS3) with profound metabolic deregulation." (PMID 36831441, 2023). "In a phase I trial, patients suffering from advanced or metastatic NSCLC, colorectal cancer, or pancreatic adenocarcinoma, and having KRAS mutations, are being enrolled to determine the efficacy of mRNA-5671 with or without pembrolizumab (NCT03948763)." (PMID 37744371, 2023). "On the other hand, other studies have shown that Fn infection is associated with KRAS mutations in colorectal cancer." (PMID 37772997, 2023).
colorectal cancer (continued). "According to a recent study, VC can selectively kill KRAS/BRAF-mutated colorectal cancer cells by targeting GAPDH." (PMID 36787291, 2023). "We demonstrated that combined administration with statins and L-OHP significantly induced apoptosis and elevated the sensitivity of KRAS-mutated colorectal cancer cells to L-OHP." (PMID 37069612, 2023). "This article aims to predict the presence of KRAS mutation in colorectal cancer patients using a CT-based radiomics model." (PMID 37626641, 2023). "KRAS mutations are also frequently found in colorectal cancer, in which approximately 35% have KRAS mutations." (PMID 37158894, 2023). "The intrinsic chemoresistance of colorectal cancer involves the enhanced cellular efflux of chemotherapy drugs with mutations of various genes (KRAS, BRAF, EGFR) and changes in respective signaling pathways." (PMID 37373047, 2023). "It was reported that KRAS mutation colorectal cancer has a poorer prognosis than wild-type KRAS colorectal cancer." (PMID 37758931, 2023). "RAS, a signal transduction molecule downstream of growth factor receptors, regulates the biological function of cells through multiple pathways and is often accompanied by KRAS gene mutation in colorectal cancer." (PMID 37777749, 2023). "KRAS/BRAF mutations (mutKRAS/mutBRAF) are unfavorable prognostic factors for colorectal cancer (CRC) metastases to the liver and lungs." (PMID 37886242, 2023). "It is worth noting that KRAS mutations are involved in up to 96% of PDACs, 52% of colorectal carcinomas, and 32% of lung adenocarcinomas." (PMID 37380804, 2023). "Epidemiologic data support an association between diet and mutations in the Kirsten-ras (KRAS) gene involved in colorectal cancer (CRC) development." (PMID 35057499, 2022). "The homo sapiens KRAS oncogene (GTPase (KRAS), transcript variant X2, mRNA—Accession number: XM_011520653), mutations of which guide treatment decisions in colorectal cancer (CRC), was used as a model gene." (PMID 35200357, 2022). "In a study focused on colorectal cancer, genomic analyses conducted on individual CTCs showed the presence of both Kirsten rat sarcoma viral oncogene homolog (KRAS) mutated and KRAS wild-type CTCs in the same patient." (PMID 35582538, 2022). "KRASG12D is the most frequent KRAS mutation in human cancer with particularly high frequencies in pancreatic and colorectal cancer." (PMID 36383067, 2022). "A uterine carcinosarcoma, an endometrial carcinosarcoma, and two stage IV colorectal cancers with respective mutations on KRAS and APC, were subjected to drug dose-response screenings with a total of 160 drugs." (PMID 35954355, 2022). "Mutations at codon 12 and position 2 (GGT-GAT) of KRAS appear to be most common in colorectal cancer." (PMID 36330448, 2022). "KRAS mutation is a critical genetic driver for the development of pancreatic cancer, colorectal cancer, and lung cancer." (PMID 35541921, 2022). "Recent studies have reported that RAS-ERK1/2 signaling induces the upregulation of Ang2 and c-x-c motif chemokine receptor 4 (CXCR4) in KRAS-mutated colorectal cancer cells, resulting in liver metastasis." (PMID 35874764, 2022).
colorectal cancer (continued). "Combination therapy of PKF115-584 (β-catenin inhibitor) and transfarnesylthiosalicylic acid (FTS, salirasib) (RAS inhibitor) can inhibit both Wnt-associated and KRAS-associated colorectal cancer." (PMID 35409064, 2022). "Colorectal cancer cells can transfer the oncogene KRAS to distant cells, predisposing them to malignant transformation (Genometastasis Theory)." (PMID 35210455, 2022). "As recovered by our progression model, KRAS mutations in colorectal cancer are known to happen after mutations in APC." (PMID 36469540, 2022). "The differences of biomarkers between colorectal cancer and its metastases have been compared, including KRAS/BRAF mutation and MSI status, indicating the importance of testing mutations in peritoneal metastasis and treating methods." (PMID 36614904, 2022). "This method detects 71.4% of BRAF and KRAS mutation profiles in stages I-IV of disease in patients with colorectal cancer in 15 min." (PMID 35484481, 2022). "As KRAS mutation is responsible for different types of cancers—lung cancer, colorectal cancer, etc.—more investigation is desirable for inhibiting KRAS oncogenes." (PMID 35409064, 2022). "Colorectal SRCC is a rare subtype of colorectal cancer with distinctive molecular characteristics, including a low incidence of KRAS, PIK3CA, and APC mutations." (PMID 34997025, 2022). "To gain further insights into the genomic landscape in KRAS-mutated colorectal cancer patients, we parsed the somatic mutation data from WES-seq and SNP array analysis." (PMID 35836817, 2022). "The combination of β-elemene and cetuximab, an ferroptosis inducer, can induce ferroptosis in the colorectal cancer cell with KRAS mutation, thus relieving the drug resistance caused by cetuximab in CRC treatment." (PMID 36387286, 2022). "A recent example is a database search to find colorectal cancer patients with a KRAS G12C mutation, noting that RAS testing data was already part of standard of care as a negative predictor of EGFR inhibitor efficacy." (PMID 36077668, 2022). "RAD21 expression in colorectal cancer cells was modulated by Wnt/β-catenin activation and was associated with shorter disease-specific survival in patients with KRAS mutant tumors." (PMID 35860572, 2022). "Compared to tons of EGFR inhibitors studied as ABCB1 reversal agents, MRTX849 showed good anticancer efficacy and safety in patients with non-small cell lung cancer and colorectal cancer with KRAS G12C mutation in clinical studies." (PMID 36104708, 2022). "Activating KRAS mutations are present in more than 20% of human cancers, even though KRAS mutation rates are dissimilar in different ethnicities and different colorectal cancer (CRC) locations." (PMID 35456940, 2022). "KRAS mutations are prevalent in 40-45% of colorectal cancer (CRC) patients, and treatment options are limited." (PMID 35911673, 2022). "They pointed out that specific epidemiological characteristics of colorectal cancer patients were associated with KRAS and BRAF mutations." (PMID 36119474, 2022). "Our study found that colorectal cancer patients with low B3GNT6 levels are more likely to develop KRAS mutations and chromosomal instability (CIN)." (PMID 35387659, 2022). "In this study, we aimed to investigate the clinicopathologic and molecular characteristics including the KRAS mutation in colorectal cancers containing a residual adenoma component." (PMID 36083889, 2022).